CCL2 (C-C motif chemokine ligand 2)
Diseases named in the same sentence as CCL2 in open-access papers (continued):
Sharing a sentence is not in itself a finding about the gene and the disease.
pulmonary sarcoidosis (5 papers, 2008 to 2025). Sarcoidosis affecting the lung parenchyma. "Plausibly, this CCR2/CCL2 axis can recruit mononuclear cells that form and expand the granulomatous disease during early inflammatory stages of pulmonary sarcoidosis." (PMID 21463523, 2011). "Upregulation of CCL2 in BAL fluid is also characteristic of patients with pulmonary sarcoidosis." (PMID 33072094, 2020). "Our analysis therefore nominated CCL2 and CCL5, both chemoattractants of mononuclear and mast cells, as well as CCL19, a chemokine implicated in T-lymphocyte recruitment, as key candidate chemokines associated with prognosis of pulmonary sarcoidosis." (PMID 26696750, 2015). "In an effort to clarify discrepancies between these studies, we performed the largest observational study involving BALF CC chemokines (CCL2, CCL3, CCL4, and CCL5) during the pathogenesis of pulmonary sarcoidosis." (PMID 21463523, 2011). "Likewise, CCL2 and CCL5 are elevated in other diseases, such as pulmonary sarcoidosis or the synovial fluid of patients with juvenile rheumatoid arthritis." (PMID 39781111, 2025). "However, CCL2 and CCL5 levels were elevated, and subgroup analysis showed higher levels of both chemokines in all stages of pulmonary sarcoidosis." (PMID 21463523, 2011).
retinal (5 papers, 2011 to 2025). "Work in mouse experimental toxoplasmic encephalitis and retinitis has identified essential roles for CCL2 and CXCL10 in the recruitment of myeloid and lymphoid cell subsets into infected tissues." (PMID 40137771, 2025). "Previous studies have shown that mice with deletions of certain chemokine such as ccl2 or chemokine receptors including ccr2 or cx3cr1 or both ccl2/cx3cr1 genes develop retinal lesions akin to human AMD." (PMID 21850237, 2011). "Using the same mice, in this study, we observed discrete patches of whitish retinal lesions in 40% of CCL2 KO mice and 24% of CCR2 KO mice (>18 month)." (PMID 21850237, 2011). "We concluded that intravitreous administration of recombinant TSG-6 might stabilize retinal lesions in Ccl2-/-/Cx3cr1-/- mice on rd8 background." (PMID 22452753, 2012).
silicosis (5 papers, 2015 to 2021). Silicosis is a respiratory disease caused by breathing in (inhaling) silica dust. "Fibrotic granulomatous lung disease together with elevated CCL2 and MMP12 gene expression as we have described in the wildtype murine MWCNT model have been reported in a rat model of chronic silicosis." (PMID 33072094, 2020).
squamous cell carcinoma (5 papers, 2019 to 2025). A carcinoma arising from squamous epithelial cells. "The previous literature had reported that CYTL1 was a small widely expressed secreted protein, which closely related to CCL2, and the expression was also downregulated in the squamous cell carcinoma of the lung." (PMID 36838330, 2023).
tuberculous meningitis (5 papers, 2009 to 2023). "The raised CCL2 responses in patients with severe disseminated D-ETB (spinal, tuberculous meningitis and abdominal TB) as compared with L-ETB, also indicate that increased CCL2 is associated with increasing disease severity." (PMID 20041183, 2009).
abscess (4 papers, 2009 to 2025). An inflammatory process characterized by the accumulation of pus within a newly formed tissue cavity which is the result of a bacterial, fungal, or parasitic infection or the presence of a foreign body. "Our data show that iKIR enhances specifically the production of pro-inflammatory cytokines known to drive proper abscess formation and improved infection outcome (IL-1β), neutrophil recruitment (CXCL1 and CXCL2), but not monocyte recruitment (CCL2) in response to MRSA skin infection." (PMID 33690673, 2021).
acne (4 papers, 2020 to 2024). An inflammatory process of the sebaceous glands which is characterized by comedones, nodules, papules and/or pustules on the skin. "The overexpression of CCL2 originated from activated TNF signaling pathway and S100A7 with chemotactic activity probably associates with some patients' side effects of “acne-flare” in early stage of isotretinoin treatment." (PMID 32685503, 2020). "Using isotretinoin for 1 week, LCN2, PTGES, and GDF15 were upregulated and might mediate sebocytes apoptosis and thus decreased sebum production; CCL2 originated from activated TNF signaling pathway and S100A7 could be related with “acne-flare”." (PMID 32685503, 2020). "Based on microarray datasets GSE10432, GSE10433, and GSE11792, upregulated expression of LCN2, PTGES, and GDF15 might mediate sebocytes apoptosis; CCL2 and S100A7 could be related with “acne-flare” using isotretinoin for 1 week." (PMID 32685503, 2020). "In conclusion, this study exhibits that the upregulated expression of LCN2, PTGES, and GDF15 might mediate sebocytes apoptosis and thus decreased sebum production; while CCL2 originated from activated TNF signaling pathway and S100A7 could be related with “acne-flare” using isotretinoin for 1 week." (PMID 32685503, 2020).
autoimmune myocarditis (4 papers, 2009 to 2023). Autoimmune myocarditis is an autoimmune disease that affects the heart. "When activated, this pathway protected organs, including heart, from the consequences of the ischemic injury, decreased levels of CCL2 and LIX after reperfusion injury, and downregulated the expression of CCL2, CCL4, CCL5, CCR1, CCR2, and CCR5 in murine autoimmune myocarditis." (PMID 27242392, 2016).
brain cancer (4 papers, 2020 to 2023). A primary or metastatic malignant neoplasm affecting the brain. "For example, astrocytes-derived exosomes enriched with miR-19a may increase brain cancer metastasis by increasing the loss of phosphatase and tensin homolog (PTEN) in tumor cells and C-C motif chemokine ligand 2 (CCL2) chemokine secretion." (PMID 33178687, 2020).
brucellosis (4 papers, 2024 to 2025). Brucellosis is a bacterial infection that spreads from animals to people via unpasteurized dairy products or by exposure to contaminated animal products or infected animals. "Additionally, we also detected high expression of typical inflammatory cytokines (e.g., S100A8/9/12, IL1B, IL6, CXCL8, CCL2, CXCL10) in brucellosis patients during the acute phase." (PMID 39135683, 2024).
Cholestatic liver disease (4 papers, 2010 to 2021). "A key event in early fibrogenesis in cholestatic liver disease is up regulation of CCL2 which results in HSC recruitment." (PMID 23840855, 2013). "This is supported in other non-granulatomous liver models; for example, in rodent models of cholestatic liver disease increased expression of CCL2 is observed three days after bile duct ligation, with CCL2 expression increasing prior to both αSMA and Col1A1." (PMID 23840855, 2013). "In conclusion, Cholangiocyte-derived exosomal H19 played a critical role in macrophage activation, differentiation, and chemotaxis through CCL-2/CCR-2 signaling pathways, which represent a therapeutic target for cholestatic liver diseases." (PMID 31940841, 2020).
chronic bronchitis (4 papers, 2015 to 2022). A type of chronic obstructive pulmonary disease characterized by chronic inflammation in the bronchial tree that results in edema, mucus production, obstruction, and reduced airflow to and from the lung alveoli. "BAL fluid from smokers with or without chronic bronchitis contained higher concentrations of CCL-2 (MCP-1) compared with non-smokers, suggesting that this chemokine is a pivotal player in LMs responses, specifically chemotaxis, in COPD." (PMID 32013028, 2020). "Sputum CCL2 levels have recently been shown to be increased in COPD subjects with chronic bronchitis compared to COPD subjects without chronic bronchitis." (PMID 26424214, 2015).
Duchenne muscular dystrophy (4 papers, 2015 to 2025). Duchenne muscular dystrophy (DMD) is a neuromuscular disease characterized by rapidly progressive muscle weakness and wasting due to degeneration of skeletal, smooth and cardiac muscle. "In addition, the nAChR-dependent modulation of CCL2 expression may also contribute to treating genetic disorders, such as the Duchenne muscular dystrophy (DMD)." (PMID 29988513, 2018).
epileptic seizure (4 papers, 2017 to 2024). "Seizure frequency was, however, lower in Q4 of CCL2 (Q1 1.5/month (0.2–8.0) and Q4 0.6/month (0.2–3.0), p-value = 0.039)." (PMID 35504954, 2022).
essential hypertension (4 papers, 2013 to 2024). Hypertension that presents without an identifiable cause. "For example, there are significantly higher levels of TNF-α, IL-1β, IL-6, and CCL2 in the PVN of SHRs, a model of primary hypertension, compared with normotensive WKYs." (PMID 31427987, 2019).
folate deficiency (4 papers, 2022 to 2025). A nutritional condition produced by a deficiency of FOLIC ACID in the diet. "However, folate deficiency induced a stronger inflammatory response, as evidenced by elevated CD14 expression and increased release of CCL2 and TNFα in cells with low folate levels compared to those with normal levels." (PMID 38881906, 2024).
geographic atrophy (4 papers, 2011 to 2016). "Up-regulation of Ccl2, Cxcl1, Cxcl10, and Cxcl11 are present in all forms of AMD, and the Ccl2/Ccr2 axis is implicated in the pathogenic accumulation of macrophages to the outer retina in models that feature aspects of either CNV or geographic atrophy, such as light damage." (PMID 26911327, 2016). "The CCL2/CX3CR1 deficient mouse may thus serve as a model for age-related atrophic degeneration of the RPE, including the dry type of macular degeneration, geographic atrophy." (PMID 23637822, 2013). "A more recent study by Luhmann and colleagues showed that “drusen”-like changes in aged CCL2-deficient mice were autofluorescent subretinal macrophages and the authors did not observe any geographic atrophy or CNV in these mice." (PMID 21850237, 2011). "In summary, we have shown in this study that aged CCL2 or CCR2 deficient mice develop certain features of atrophic, but not angiogenic AMD-like changes, and as such, may represent an animal model for early stage human geographic atrophy." (PMID 21850237, 2011).
gynecological cancer (4 papers, 2018 to 2024). "Among the 10 most closely associated proteins identified in this analysis, the CCL2 -2518A/G polymorphism is reportedly closely related to the risk of gynecological cancer." (PMID 38807156, 2024). "The meta-analysis demonstrated a noteworthy association between CCL2-2518A/G polymorphism and the risk of gynecological cancer, and the association varied by ethnicity." (PMID 29458367, 2018). "This study identified CCL2-2518A/G genetic polymorphism is associated with gynecological cancer risk." (PMID 29458367, 2018). "Our data demonstrated the CCL2-2518A/G (rs1024611) polymorphism is significantly associated with risk of gynecological cancer, and the association differs by ethnicity." (PMID 29458367, 2018). "The -2518A/G (rs1024611) polymorphism of the CCL2 (C-C motif chemokine ligand 2), also known as MCP-1 (monocyte chemotactic protein-1) gene, has been reported to be associated with increased gynecological cancer risk, but the results are conflicting." (PMID 29458367, 2018). "First, because this study was used to analyze the association between CCL2 and gynecological cancer risk, the number of articles identified is relatively smaller than other researches that explored all types of cancers." (PMID 29458367, 2018). "Six articles focused on the association between CCL2-2518A/G (rs1024611) polymorphism, and gynecological cancer risk was selected and data were extracted." (PMID 29458367, 2018). "We conducted a meta-analysis to further explore the association between CCL2 polymorphism and gynecological cancer risk." (PMID 29458367, 2018). "In this analysis, 1089 cases and 1553 controls from six publications were used to investigate the association between CCL2-2518A/G (rs1024611) polymorphism and the risk of gynecological cancer with a meta-analytic approach." (PMID 29458367, 2018). "The meta-analysis showed that CCL2-2518A/G (rs1024611) polymorphism is associated with risk of gynecological cancer (GG vs AG + AA, OR = 1.55, 95%CI = 1.07–2.24, P < 0.05; AA vs GG, OR = 0.59 95%CI = 0.38–0.92, P < 0.05)." (PMID 29458367, 2018). "Indeed, ORs of dominant GG vs AG + AA model and heterozygous AA vs GG model were 1.55 (95%CI = 1.07–2.24, P < 0.05) and 0.59 (95%CI = 0.38–0.92, P < 0.05) respectively, indicating a significant association between CCL2-2518A/G and gynecological cancer risk." (PMID 29458367, 2018). "Thus, we performed this meta-analysis to assess the association between CCL2-2518A/G and gynecological cancer risk." (PMID 29458367, 2018). "Many additional cytokines and chemokines regulate the expression of CCL2 and co-mediate gynecological cancer in addition to IL-1." (PMID 36403055, 2022). "According to previous studies, CCL2 plays a significant role in the occurrence and development of gynecological cancers." (PMID 36403055, 2022). "Finally, 6 articles were selected into this study after 41 articles that were not related to CCL2-2518A/G (rs1024611) polymorphisms and gynecological cancer were excluded." (PMID 29458367, 2018).
hearing loss (4 papers, 2017 to 2024). "Further investigations have demonstrated that anti-inflammatory medications effectively reduce CCL2 levels and ameliorate hearing loss." (PMID 39677857, 2024). "On the other hand, we previously reported an association between CCL2 rs1024611 and sensorineural hearing loss in cCMV." (PMID 34578364, 2021). "Future research directions encompass more refined analyses for different types of hearing loss, in-depth exploration of the relationship between CCL family members (particularly CCL2) and hearing loss, and prospective studies in both animal models and human populations." (PMID 39677857, 2024). "Finally, the analysis of association between SNPs in the CCL2 gene and hearing loss involved only infants with early-onset SNHL." (PMID 28501927, 2017). "Notably, CCL2 plays a pivotal role in the pathogenesis of hearing loss." (PMID 39677857, 2024). "Although this study emphasizes the key role of CCL19 in hearing loss, current research findings suggest that further investigation of the CCL family, especially CCL2, is necessary." (PMID 39677857, 2024).
Huntington disease (4 papers, 2012 to 2025). Huntington disease (HD) is a rare neurodegenerative disorder of the central nervous system characterized by unwanted choreatic movements, behavioral and psychiatric disturbances and dementia. "Previous multi-cohort meta-analyses and experimental studies confirmed that MMP9 and S100A8/A9 contribute to microglial activation and neuronal injury, while CCL2 signaling has been linked to neurodegeneration and immune cell recruitment in Huntington’s disease." (PMID 41614741, 2025).
hypercoagulability (4 papers, 2013 to 2022). "Consistent with this view, hypercoagulability promoted a significant increase in plasma CCL2 and CXCL1 levels." (PMID 23409043, 2013).
inflammatory bone diseases (4 papers, 2019 to 2025). "In addition, SCSP modulates inflammatory cascades by attenuating IL-17 signaling, Toll-like receptor pathways, and key genes implicated in inflammatory bone diseases, such as Ccl2, Il17re, Fosl1, Mmp13, Ccl5, Tlr1, Il12b, and Atp6v1b1." (PMID 40926992, 2025). "Interestingly, simvastatin reduced TNF-α-induced synthesis of Cysteine-rich 61 (Cyr61) and chemokine ligand 2 (CCL2) that are potential osteolytic mediators in inflammatory bone diseases, in human OB, thereby decreasing bone loss." (PMID 30936777, 2019). "Cysteine-rich 61 (Cyr61) and CCL2 are potential osteolytic mediators in inflammatory bone diseases." (PMID 32252793, 2020).
interstitial nephritis (4 papers, 2015 to 2024). Inflammation of the renal tubules and supporting tissues of the kidney. "Egr-1 deficiency in primary renal tubuloepithelial cells isolated from mice could weakly respond to pro-inflammatory and pro-fibrotic stimuli ex vivo, and Egr1−/− mice with tubulointerstitial nephritis expressed less TNFα and CCL2." (PMID 38397780, 2024).
intrahepatic cholangiocarcinoma (4 papers, 2018 to 2024). A carcinoma that arises from the intrahepatic bile duct epithelium in any site of the intrahepatic biliary tree. "Fittingly, in human intrahepatic cholangiocarcinoma, high expressions of stromal FAP and CCL2 were negatively associated with ICC patient survival." (PMID 34804061, 2021). "Fibroblast activation protein (FAP)-mediated progression of intrahepatic cholangiocarcinoma (ICC) can be abrogated by anti-Gr-1 antibody treatment, as FAP mediates the infiltration of MDSCs in ICC via inducing CCL2 expression to promote tumor progression and angiogenesis." (PMID 38397901, 2024). "In a murine liver tumor model, it was also shown that FAP+ CAFs are a major source of CCL2 and that fibroblastic STAT3-CCL2 signaling promotes tumor growth by enhancing the recruitment of MDSCs, which also predicts poor prognosis of patients with intrahepatic cholangiocarcinoma." (PMID 29545811, 2018).
monocytic leukemia (4 papers, 2015 to 2024). "We herein report the effect of 19 plant extracts on TNF-α and CCL2 release by lipopolysaccharide- (LPS-) stimulated THP-1 cells, a human monocytic leukemia cell line, along with their radical scavenging activity on DPPH." (PMID 25878716, 2015). "It is not clear why, in patients with monocytic leukemias, lower plasma levels of CCL2 or its relevance were observed." (PMID 28045930, 2017).
mucositis (4 papers, 2017 to 2023). Mucositis is inflammation and damage of the mucous membranes lining the mouth and other parts of the gastrointestinal (GI) tract. "In contrast to our findings on inflammatory markers, our study suggests that local production of immune-modulating chemokines CCL2, CCL7 and KC, coupled with the increase in macrophages and neutrophils within the lamina propria, plays a key role in Doxo-induced mucositis." (PMID 28257503, 2017). "During the treatment of peri-implant mucositis and peri-implantitis there were minimal effects of non-surgical treatment alone on the investigated inflammatory biomarkers (IL-4, IL-10, and IL-12, TNF-a, RANKL, OPG IL-1β, IL-6, TNF-α, MCP-1/CCL2, MIP-1α/CCL3, IFN-γ, MMP-8, sRANKL, OPG and G-CSF)." (PMID 36360962, 2022).
Myalgia (4 papers, 2018 to 2026). "CRP was significantly higher in patients with these symptoms, while chemokines CCL2 (MCP-1), CCL3 (MIP-1α) and CXCL8 (IL-8) were higher in patients with rigors and myalgia." (PMID 41027884, 2025).
obstructive sleep apnea (4 papers, 2014 to 2022). "Noteworthy among these was Ccl12/MCP-5, a structural and functional homologue of human Ccl2/MCP-1 that is increased in obstructive sleep apnea syndrome, a sleep disorder characterized by SF." (PMID 34947814, 2021).
post-traumatic stress disorder (4 papers, 2016 to 2023). An anxiety disorder precipitated by an experience of intense fear or horror while exposed to a traumatic (especially life-threatening) event. "Clinical studies have demonstrated an increase in CCL5 and CCL2 serum levels in subjects displaying generalized anxiety disorder, chronic stress, and post-traumatic stress disorder (PTSD)." (PMID 34863117, 2021). "In the same line, related studies showed an increase in ENA-78/CCL5 and MCP-1/CCL2 serum levels in subjects displaying generalized anxiety disorder, chronic stress, and post-traumatic stress disorder." (PMID 34863117, 2021).
primary biliary cholangitis (4 papers, 2014 to 2025). Primary biliary cholangitis (PBC) is a chronic and slowly progressive cholestatic liver disease of autoimmune etiology characterized by injury of the intrahepatic bile ducts that may eventually lead to liver failure. "Studies have shown a positive correlation between serum CCL2 levels and fibrosis severity in primary biliary cholangitis (PBC) patients." (PMID 39850880, 2024).